FUT6 (fucosyltransferase 6)
Diseases named in the same sentence as FUT6 in open-access papers (continued):
Sharing a sentence is not in itself a finding about the gene and the disease.
tumor (19 papers, 2010 to 2025). "In this experiment, our gain- and loss-of-function analyses showed that altered FUT5 and FUT6 regulated cell proliferation, migration, and invasion in vitro and tumour growth in vivo." (PMID 28771224, 2017). "In this study, the combination of the GEPIA online database and the GSE161533 microarray dataset was applied to investigate the FUT6 expression profile in tumor tissue samples of patients with ESCA." (PMID 39375968, 2024). "The expression level of FUT6 in tumours was further studied by immunohistochemical analysis, which showed that the FUT6-overexpressing group had greater FUT6 expression than the control group." (PMID 38807207, 2024). "Our findings provide an indication that FUT6 acts as a tumor suppressor gene, exerting an anti-tumor effect on ESCA." (PMID 39375968, 2024). "Immunohistochemical and qRT-PCR results revealed that FUT6 was underexpressed in tumour tissues and HNC cells." (PMID 38807207, 2024). "FUT6 overexpression notably impeded tumour growth, as indicated by decreases in tumour weight and volume." (PMID 38807207, 2024). "In this study, we obtained the ESCA-related microarray dataset GSE161533 from the GEO database and found that FUT6 expression was downregulated in tumor tissue samples from patients with ESCA using GEO2R analysis." (PMID 39375968, 2024). "For this, we evaluated the general expression of fucosylation-related genes detected in tumour cells using gene sets associated with the GDP-Fuc synthesis (GMDS, TSTA3), fucosyltransferases (FUT2, FUT3, FUT4, FUT6) or both." (PMID 35017635, 2022). "Overexpression of FUT6 inhibits the malignant activity of tumor cells by inhibiting the dimerization and phosphorylation of the epidermal growth factor receptor." (PMID 36510584, 2022). "Overexpression of FUT6 inhibited the malignant activities of neoplasm cells by suppressing the dimerization and phosphorylation of epidermal growth factor receptors." (PMID 35127477, 2021). "Established cultured cell lines can present differences in term of glycosylation compared to observations made in human tissues, thus to better mimic tumor versus normal cells, we chose to use the fucosyltransferase 6 (FUT6) transfected SW620 cell line." (PMID 33167483, 2020). "Altogether, these findings confirmed that FUT5 and FUT6 possess tumour stimulating activities in CRC tumours, which was regulated by miR-125a-3p." (PMID 28771224, 2017). "The results showed that miR-125a-3p, FUT5 and FUT6 are differentially expressed in normal and tumour tissues." (PMID 28771224, 2017). "The expression of sialyl-Lewis × in tumor cells is regulated by members of the α1,3 fucosyltransferase (α1,3FuT) family, and in particular by FuT6." (PMID 20459627, 2010). "Cell and animal experiments showed that overexpression of FUT6 could inhibit tumour proliferation and migration." (PMID 38807207, 2024). "These interesting results of FUT6 in tumour cells suggest that FUT6 may play different roles in different cancer types." (PMID 38807207, 2024). "Similarly, the examination using the GEPIA data indicated a significant decrease in FUT6 expression in the 182 ESCA tumor samples compared with the 286 corresponding normal or para-cancerous tissues." (PMID 39375968, 2024). "After analyzing the microarray samples, it was found that fucosyltransferase 6 (FUT6) was downregulated in tumor tissue samples of patients with ESCA, suggesting that FUT6 may be a key gene affecting the behavior of cells in ESCA." (PMID 39375968, 2024). "Similarly, in vivo experiments demonstrated that the proliferative capacity of tumour cells decreased after FUT6 was overexpressed." (PMID 38807207, 2024). "Based on the expanded correlation analysis results, we found that ACOX1, ALDH2, FUT6, and LRRC19 have a high association with GPX3 and DIO1 in the TCGA database, whether it is only tumor samples or “tumor samples + normal samples”." (PMID 32316597, 2020).
tumor (continued). "In conclusion, our study demonstrated that overexpression of miR-125a-3p attenuated the migration, invasion and angiogenesis of CRC cell lines and inhibited tumour growth in vivo by affecting FUT5 or FUT6 regulated expression through the PI3K/Akt signalling pathway." (PMID 28771224, 2017). "Correspondingly, immunostaining analysis of FUT5 or FUT6 was performed in harvested tumour tissues." (PMID 28771224, 2017). "Taken together, FUT6 overexpression in SW620 cells has a first direct, and expected, consequence of elevating the amount of sLeX antigen, but seems also to have an indirect influence on the expression of other N-glycan structures associated with tumor progression." (PMID 33167483, 2020). "Focusing on glycosyltransferases expression in tumor tissues, we observed two distinct expression clusters, segregating FUT3, FUT4, FUT6, and ST3GAL4 transcripts, from FUT7, FUT9, ST3GAL3, and ST3GAL6." (PMID 39508360, 2025). "In order to investigate the effect of downstream FUT6 on malignant biological behavior of tumor cells, we then constructed two cell lines HN4 and FaDu that overexpressed FUT6." (PMID 38807207, 2024). "FUT6 is a member of the fucosyltransferase (FUT) family, which promotes tumor metastasis, proliferation, and poor prognosis." (PMID 36330441, 2022). "FUT5 and FUT6 can be used as direct targets of miR-125a-3p, and miR-125a-3p/FUT5-FUT6 attenuates angiogenesis in CRC cells and inhibits tumour growth by affecting the PI3K/AKT signalling pathway." (PMID 33865381, 2021). "Our data demonstrated that tumor tissues contained significantly lower mRNA levels of FUT3 (2.3 fold), FUT4 (2.7 fold), FUT5 (5.9 fold), FUT6 (3.0 fold), FUT8 (2.0 fold), and FUCA1 (2.6 fold) as compared to adjacent normal tissues." (PMID 34703796, 2021). "Numerous experimental studies indicated that the expression of FUT6/sLex positively impacts malignancy of CRC cells by modulating migration, proliferation and tumor formation." (PMID 32911675, 2020). "In SW620 xenograft tumours, miR-125a-3p overexpressing tumours showed low FUT5 and FUT6 protein levels, and FUT5 or FUT6 protein reduced in the SW620/FUT5 shRNA or SW620/FUT6 shRNA group." (PMID 28771224, 2017). "These in vivo experimental results showed that overexpression of FUT6 could block tumor growth, while low expression of lncRNA PART1 could promote tumor growth." (PMID 38807207, 2024). "After 4 weeks, the growth of tumours transfected with anti-miR-125a-3p, SW480/FUT5, and SW480/FUT6 significantly increased compared to the control, whereas tumour growth was significantly decreased in the nude mice transfected with miR-125a-3p-mimics, SW620/FUT5 shRNA or SW620/FUT6 shRNA." (PMID 28771224, 2017).
cancer (16 papers, 2016 to 2024). A tumor composed of atypical neoplastic, often pleomorphic cells that invade other tissues. "Therefore, as increased FUT6 expression is associated to similar roles in different cancer types, FUT6, sLeX antigen and E-selectin ligands are potentially promising therapeutic targets for cancer treatment." (PMID 33167483, 2020). "Accordingly, it remains to be examined a significance of poorly expressed fucosylated glycans in such a cancer patient with FUT6-deficiency (details of molecular and enzymatic studies on fucosylation of AGP in patient N with FUT6-deficiency will be published elsewhere)." (PMID 27295180, 2016). "Therefore, until now, the occurrence of cancer-associated changes in the fAGP level in diverse cancer types has been clarified together with the elucidation of the FUT6 genes and α1,3fucosyltransferase as its key molecules although the total number of measurements was limited." (PMID 39795568, 2024). "Surprisingly, enzymes responsible for the biosynthesis of well-known cancer-associated structures, such as β1,6 branching (MGAT5), sialyl-Tn (ST6GALNAC1) sLex (FUT6), Sia6LacNAc (ST6GAL1), and core-fucosylation (FUT8) lack any relationship with survival." (PMID 33919332, 2021). "In normal colon, sLex is expressed by only a few specimens, and the level of antigen expression is much lower than that in cancer samples, but the expression level of FUT6 is quite similar in normal and cancer colon tissues." (PMID 34771437, 2021). "Similar observations were made in other cancer types where FUT6 overexpression resulted in E-selectin ligand expression and higher migration capability." (PMID 33167483, 2020). "The expression of miR-125a-3p was significantly decreased in CRC tissues compared with normal tissue, whereas the expression levels of FUT5 and FUT6 were significantly upregulated in cancer tissue." (PMID 28771224, 2017). "LncRNA PART1 and FUT6 play critical roles in tumorigenesis and cancer progression." (PMID 38807207, 2024). "Therefore, the influence of lncRNA PART1 on the proliferation, apoptosis and migration of cancer cells may occur through regulation of the translation and transcription of FUT6." (PMID 38807207, 2024). "In other words, cancer types exhibiting higher FUT methylation are more sensitive to targeted therapies with the exception of FUT1 and FUT6, suggesting that cancer cells can inhibit fucosylation upon increased methylation of FUT promoter are more susceptible to therapy." (PMID 36961502, 2023). "It was reported that miR-106b may stimulate cancer cell growth through targeting DAB2, FUT6, MYC, and multiple mechanisms." (PMID 34519258, 2021).
infection (2 papers, 2023 to 2024). The state of being infected such as from the introduction of a foreign agent such as serum, vaccine, antigenic substance or organism. "Additionally, we identified 10 genomic regions associated with breakthrough infection (SLC6A20, ST6GAL1, MUC16, FUT6, MXI1, MUC4, HMGN2P18-KRTCAP2, NFKBIZ and APOC1), and one with breakthrough severity (APOE)." (PMID 39384777, 2024).
adenocarcinoma (1 paper, 2025). A common cancer characterized by the presence of malignant glandular cells. "Its identification and overexpression, promoted by FUT6/sLeX in an adenocarcinoma cell line with epithelial morphology, pose a provocative hypothesis." (PMID 39508360, 2025).
FUT6 also shares sentences with these, for which no sentence is quoted: hepatocellular carcinoma (6 papers); asthma (1); clear cell renal cell carcinoma (1); congenital disorder of glycosylation (1); Diabetes (1); endometriosis (1); Esophageal Carcinoma (1); gastric cancer (1); glioblastoma (1); lung adenocarcinoma (1); lung carcinoma (1); lymphoma (1); malignant meningiomas (1); metastatic colorectal cancer (1); Obesity (1); type 2 diabetes (1).